SSTR1 (somatostatin receptor 1)
Diseases named in the same sentence as SSTR1 in open-access papers (continued):
Sharing a sentence is not in itself a finding about the gene and the disease.
tumor (continued). "Similarly, mRNA for the somatostatin receptors, SSTR1 (P < 0.01) and SSTR2 (P < 0.001), which are associated with somatostatin analogue therapy, were differentially expressed across all tumor samples." (PMID 40217502, 2025). "We thus hypothesized that augmenting SSTR1 expression or SSTR1 signaling (e.g., using an agonist) may suppress tumor growth and serve as a therapeutic avenue for ARSI-resistant PCa." (PMID 39352383, 2024). "Another study correlated the increased expression of SSTR1 with increased tumor suppression." (PMID 39329930, 2024). "However, sparsely distributed studies support a relation between the expression level of SSTR1 subtypes and tumor stage and lymph node metastasis." (PMID 38203605, 2023). "The SST-mediated in vivo and/or in vitro antiproliferative effect in the tumour is considered direct via activation of five different somatostatin receptor subtypes (SSTR1-5), which are well expressed in most tumours and often more than one receptor in a single cell." (PMID 38203605, 2023). "Univariate analysis demonstrated a higher rate of tumor recurrence for increased expression scores for SSTR2A, SSTR3, and SSTR4 (p = 0.0312, p = 0.0351, and p = 0.0390, respectively), while high expression levels of SSTR1 showed less frequent tumor recurrences (p = 0.0012)." (PMID 34601710, 2022). "Hyper-accessible 5′-UTR at SSTR1 in tumor contribute to the expression of SSTR1 mRNA." (PMID 35947334, 2022). "It has earlier been demonstrated in a mouse tumor model that the endocytosed receptors are predominantly recycled, and that the de novo synthesis is low for SSTR1- SSTR4, whereas SSTR5 is the only receptor which is stored intracellularly and can rapidly be recruited." (PMID 34822040, 2021). "Additionally, an elevated expression of SSTR1 in tumor cells has been reported in patients diagnosed with advanced-stage HCC." (PMID 33672651, 2021). "Except for somatostatin receptor 1, expression patterns differed between the three tumor types." (PMID 31336364, 2019). "SSTR1 was present in all normal samples and in 3 out of 5 tumor samples." (PMID 27927191, 2016). "In addition, expression of SSTR1 was present in both primary normal and matched tumor colon samples, as well as, in the normal only tissue samples analyzed (data not shown)." (PMID 27927191, 2016). "For this reason, enhancing SSTR expression in tumor cells could make them more susceptible to growth inhibition by SSTR agonists, particularly SSTR1 agonists, as anti-neoplastic treatment." (PMID 16018813, 2005). "Therefore, SSTR1 activation appears to be a potentially important mechanism for tumor cell growth control." (PMID 16018813, 2005). "SSTR1 has been shown to inhibit cell proliferation and migration of tumor cells." (PMID 16018813, 2005). "Even for grade II meningiomas that show a high expression of SSTR2A, good expression was also seen for SSTR1 and 5, implying that PRRT targeting all SSTRs, but especially SSTR1, 2A, and 5, may be beneficial in delivering radiation to tumor cells more sufficiently." (PMID 33899156, 2022). "Therefore, we speculate that smsDX could bind with SSTR1 or 2 on the surface of macrophages and break the paracrine loop between the tumor and the inflammatory microenvironment, thereby alleviating the macrophage-stimulated progression of PCa." (PMID 26010447, 2015). "Likewise, the observed up-regulation of SSTR1 by Tam may represent an important mechanism whereby Tam exerts an inhibitory effect on tumor progression." (PMID 16018813, 2005). "Namely, various studies based on immunohistochemistry demonstrated the expression of all SSTR1 to SSTR5 on primary NB and, specifically, the overexpression of SSTR2 in the majority of NBs, even in recurrent/refractory tumor disease." (PMID 40064181, 2025). "SST exerts direct anti-tumor effects by direct binding to and activation of one or more of five different SST receptors (SSTR1-5), with SSTR2 representing an inhibitory G protein-coupled receptor." (PMID 40134804, 2025).
tumor (continued). "SPT suppressed tumor growth and prolonged the survival of host mice in 2 enzalutamide-resistant models, LuCaP 35CR-ENZR and LuCaP 96CR-ENZR, and SSTR1 expression increased after SPT in both models." (PMID 39352383, 2024). "For lung NECs, the predominant SSTRs are SSTR2A and SSTR1, with SSTR4 and SSTR5 less frequently expressed, depending on the degree of differentiation of the tumor." (PMID 39329930, 2024). "By Reubi and Waser, most GLP-1R-positive tumours showed SSTR2, while the expression of SSTR1, 3, 4 and 5 was lower." (PMID 37894845, 2023). "Within the 18 tumour specimens, SSTR2A showed the highest immunoreactivity with a median IRS of 8, while SSTR1, SSTR2B und SSTR5 had a median IRS of 3 and SSTR3 und SSTR4 showed no immunoreactivity (median IRS = 0)." (PMID 37707754, 2023). "Six different somatostatin receptor types (SSTR1, SSTR2A, SSTR2B, SSTR3, SSTR4, and SSTR5) have been detected in numerous different human tissues as well as several tumor types." (PMID 33899156, 2022). "Regarding membrane receptor gene expression, we found that SSTR1, DRD4 and DRD5 expression was higher in responder tumours at both three and six months after treatment." (PMID 29266696, 2018). "The monoclonal antibodies against SSTR1, SSTR2, SSTR3, SSTR5, and CXCR4 produced distinct immunostaining of the plasma membrane, but also of the cytoplasm of the HCC and CCC tumor cells." (PMID 29282035, 2017). "We determined, by conventional RT-PCR, if somatostatin (SST) and its receptors (SSTR1-5) are expressed in SW480 and HT29 cells as well as in matched fresh normal and tumor human colon tissue samples." (PMID 27927191, 2016). "SST receptors have also been reported to be differentially expressed in various tumor types, and our data from different CRC tissue samples supports the expression of SSTR1." (PMID 27927191, 2016). "In our study, we first looked at the expression of ALDH and SSTR1 in different CRC cell lines, as well as, in matched normal and tumor tissue samples." (PMID 27927191, 2016). "Of note, at the protein level, SSTR1+ cells were expressed in all CRC cell lines and normal and tumor colon tissue samples." (PMID 27927191, 2016). "The proportion of SCs to NECs cells was quantified, by flow cytometry, in CRC cell lines and primary normal/tumor tissues based on cellular ALDH and SSTR1 levels, respectively." (PMID 27927191, 2016). "An MSP survey of 100 tumor tissue samples demonstrated that hypermethylation of the SST promoter (81%) and SSTR1 promoter (64%) occurred with a high frequency." (PMID 25734919, 2015). "Reportedly, the cultured tumor cells IMR32 and CFPAC-1 highly express some SSTRs, with BON cells natively expressing high levels of SSTR1, SSTR2 and SSTR5." (PMID 21892324, 2008). "It has been previously shown that SSTR1 and SSTR2 are highly expressed in breast cancer cells and exert an inhibitory role on tumor cell proliferation and migration." (PMID 16018813, 2005). "PMT cells express various somatostatin receptors (SSTR1, 2A, 2B, 3, 4, 5), and 68Ga-DOTATATE, an SSTR antagonist, binds to these receptors, leading to receptor internalization and the accumulation of radioactivity within tumor cells (Jan de Beur, 2005)." (PMID 39866529, 2025). "Using a recently published single-cell RNA-Seq dataset of mCRPC biopsies, we found that SSTR1 expression was predominantly restricted to PCa cells and absent in the tumor immune microenvironment." (PMID 39352383, 2024). "SSTR1 was expressed in three (75%), SSTR3 in two (50%), SSTR4 in 0% and SSTR5 in 0% of the GLP-1R-negative tumours, compared to eleven (23%) (p = 0.055), fifteen (31%) (p = 0.589), 0% and three (6%) (p = 1.000) in GLP-1R-positive tumours, respectively." (PMID 37894845, 2023). "Tumors were divided into two groups according to aggressiveness, the non-aggressive group (n = 19) had higher SSTR5 and SSTR1 expression than the aggressive (n = 16) tumor group." (PMID 35008325, 2021).
tumor (continued). "Subsequently, through OCLR scores, it was further confirmed that the expressions of FGF17, PRKCG, SSTR1, and SCTR were different in KIRC, which might lead to tumor metastasis by promoting tumor dedifferentiation." (PMID 35155566, 2021). "Moreover, individual ROC curve analysis of SSTR1-4 expression was capable of accurately discriminate tumour and non-tumour samples, with an Area Under the Curve (AUC) > 0.8." (PMID 40268793, 2025). "Moreover, mRNA expressions of CA14, RPE65, IGSF1, SLC18 A2 and CPNE6 were significantly lower in PCa samples compared to benign samples, while HJURP, COMP, KRTAP5-1, VGF, SSTR1, LINC01612, NAALADL2-AS2, AMH and ARHGDIG were elevated in tumor samples (p < 0.05)." (PMID 40592939, 2025). "Additionally, G-CIMP negative tumours (representing a more aggressive GBM phenotype) have significantly lower expression levels of SSTR1 and/or SSTR2, but not CORT (data not shown), in the TCGA/Gravendeel/Murat-cohorts." (PMID 40268793, 2025). "Since SSTR1 is downregulated after ARSI, we examined the reciprocal relationship between the AR/FOXA1/HOXB13 transcription machinery and SSTR1 expression, specifically the effect of testosterone (as opposed to ADT and ARSIs) on SSTR1 expression and tumor growth." (PMID 39352383, 2024). "Moreover, we observed that lower SSTR1 and SSTR2, but not CORT, expression levels were also displayed in tumours harbouring EGFR amplification, another aggressive sign in GBM, in the Gravendeel-cohort." (PMID 40268793, 2025). "Meningiomas that were treated with radiotherapy before resection had significant lower scores for SSTR1 (5.4 compared to 6.6, p = 0.0007) and SSTR5 (4.3 compared 4.9, p = 0.0340), while expression of SSTR2A, 3, and 4 were similar to tumor tissue that did not receive radiotherapy." (PMID 33899156, 2022).
cancer (19 papers, 2015 to 2025). A tumor composed of atypical neoplastic, often pleomorphic cells that invade other tissues. "In humans, SSTR1 has been revealed to be associated with cancers and tumors, and its selective agonists have been used as cancer therapies." (PMID 35052417, 2021). "The NETest is a liquid biopsy test for NENs that improves the accuracy of cancer molecular diagnosis by detecting NET-associated genes, such as Ki-67, SSTR1, and SSTR2 expression levels through reverse transcription polymerase chain reaction." (PMID 38835066, 2024). "The endogenous cyclic tetradecapeptide SST14 was reported to stimulate all five somatostatin receptors (SSTR1–5) for hormone release, neurotransmission, cell growth arrest and cancer suppression." (PMID 35595746, 2022). "Quantitative RT-PCR of SST1 and SSTR1 transcripts from 10 UM-SCC cell lines revealed lower expression in cancer cell lines than in normal fibroblasts (P < 0.01)." (PMID 25734919, 2015). "Downregulation of SSTR1 in patients with PCa whose disease is progressing while on ARSIs is consistent with the known antitumor effect of somatostatin and somatostatin analogs observed in other cancer types (e.g., gastrointestinal and pancreatic NE tumors)." (PMID 39352383, 2024). "Our results showed that the antagonist of SSTR1 decreased BMMSC migration toward cancer spheroids." (PMID 39554905, 2024). "SSTR1 expression is high in primary, untreated PCa and appears to be restricted to cancer cells." (PMID 39352383, 2024). "In epithelial-origin cancers, EBV infection has been strongly associated with the gain of CpG methylation, and methylation of tumor suppressor genes such as p14, p16, IHH, TRADB, PTEN or SSTR1 is likely the key mechanism of oncogenesis." (PMID 32841292, 2020). "In summary, we found significant differences in the expression of FGF17, PRKCG, SSTR1, and SCTR in cancer, which are correlated with immune response and adjuvant therapy." (PMID 35155566, 2021). "In addition to the C3, for these genes (CXCL8, CX3CR1, GRM8, HTR1B, HTR1D, PTGER3, SSTR1 and SUCNR1) were related to survival in the ACC and it was also could be useful in other cancers 24-31." (PMID 34220331, 2021).
infection (2 papers, 2010 to 2018). The state of being infected such as from the introduction of a foreign agent such as serum, vaccine, antigenic substance or organism. "The data indicated that on day 14 post-infection, SSTR1 and SSTR2 mRNA levels were significantly increased." (PMID 29522573, 2018). "The quantitative PCR results demonstrated that on day 14 post-infection, SSTR1, SSTR2 and SSTR3 mRNA comprised approximately 85%, 12.5%, and 2.5% of SSTR subtypes, respectively in the unweaned rat model." (PMID 29522573, 2018). "On day 50 post-infection, previously infected, octreotide-treated animals exhibited significantly elevated levels of SSTR1, SSTR2 and SSTR3 mRNA compared with previously infected, untreated rats (p<0.05 and p<0.01, respectively)." (PMID 29522573, 2018). "The present study demonstrated that octreotide therapy, administered at 50 μg/kg/day by intraperitoneal injection from day 10 to 17 post-infection, decreased mRNA levels of SSTR1 and SSTR2 on day 14 post-infection, although it increased mRNA levels of SSTR1, SSTR2 and SSTR3 on day 50 post-infection." (PMID 29522573, 2018). "Interestingly, SSTR1 showed continual down-regulation at both 8 hours and 4 days post-infection." (PMID 21172007, 2010). "Real-time PCR analysis indicated that in the inflamed jejunum, a significant increase in SSTR1 and SSTR2 expression was observed on day 14 post-infection." (PMID 29522573, 2018). "Octreotide therapy down-regulated the expression of SSTR2 on day 37 post-infection but significantly increased expression of SSTR1, SSTR2 and SSTR3 on day 50 post-infection." (PMID 29522573, 2018). "The levels of jejunal SSTR1, SSTR2 and SSTR3 mRNA transcripts increased by more than 98% from day 14 to day 37 post-infection." (PMID 29522573, 2018). "Following the period of intestinal parasite clearance, by day 14 post-infection, the mRNA levels of SSTR1, SSTR2, but not SSTR3 were significantly higher in the tissues extracted from the jejunum of C. parvum-infected animals compared with those of the control animals (p<0.05)." (PMID 29522573, 2018). "SSTR1 and SSTR3 mRNA transcript levels were not significantly increased in previously infected, untreated animals on day 37 post-infection compared to the infected, treated and non-infected control groups." (PMID 29522573, 2018). "Although SSTR1 and SSTR2 expression levels were increased following infection, SSTR3 mRNA was not significantly modified on days 14, 37 and 50 post-infection." (PMID 29522573, 2018).
Head and neck tumor (1 paper, 2015). "To test this hypothesis, we studied methylation of the SST and SSTR1 promoters by Q-MSP in 100 head and neck tumors of differing primary sites." (PMID 25734919, 2015).
hematological diseases (1 paper, 2020). "Therefore, in our present study, we aimed to investigate the expression of mRNA for SSTR subtypes (SSTR-1–5) in samples from human pediatric solid tumors as well as bone marrow aspirates and peripheral blood of children with hematological diseases." (PMID 33297556, 2020).
SSTR1 also shares sentences with these, for which no sentence is quoted: Anxiety (2 papers); Huntington disease (2); lung carcinoma (2); paraganglioma (2); pituitary tumor (2); anorexia nervosa (1); breast adenocarcinoma (1); colitis (1); endometrial cancer (1); glioblastoma (1); gynecologic cancers (1); head and neck cancer (1); hepatocellular carcinoma (1); Hodgkins lymphoma (1); Hypoglycemia (1); Insulin resistance (1); intestinal infection (1); leiomyoma (1); liver cancer (1); lung carcinoid (1); lymphoma (1); medullary thyroid cancer (1); medulloblastoma (1); melanoma (1); Merkel cell carcinoma (1); nasopharyngeal carcinoma (1); neurofibromatosis type 2 (1); non-alcoholic fatty liver disease (1); non-Hodgkin lymphoma (1); oral cavity cancer (1).
A further 11 diseases each share a sentence with SSTR1 in 1 paper.